PART1 (prostate androgen-regulated transcript 1)
Diseases named in the same sentence as PART1 in open-access papers (continued):
Sharing a sentence is not in itself a finding about the gene and the disease.
dental caries (1 paper, 2023). The decay of a tooth, in which it becomes softened, discolored, and/or porous. "After adjusting for sex and ethnicity, carriers of the PART1 rs27565 TC or CC genotype who ate sugary food more than once a week had a 1.6-fold increase in their risk of dental caries compared to TT carriers who ate sugary food at most once a week (OR = 1.579, 95% CI = 1.032–2.414, P value = 0.035)." (PMID 36597064, 2023). "The aim of this study was to assess associations of PART1 rs27565 and DEFB1 rs11362 polymorphisms with the prevalence of dental caries in twelve-year-old children in Nandan County, Guangxi, China." (PMID 36597064, 2023). "This study focused on PART1 rs27565 and DEFB1 rs11362 polymorphisms due to their previous potential association with dental caries." (PMID 36597064, 2023). "Carriers of the PART1 rs27565 TC + CC genotype and the DEFB1 rs11362 CT + TT genotype who ate sugary food more than once a week had a higher risk of developing dental caries." (PMID 36597064, 2023). "Our results showed that carriers of the PART1 rs27565 C allele and the DEFB1 rs11362 T allele had higher risks of dental caries." (PMID 36597064, 2023).
disc degeneration (1 paper, 2022). "The lncRNA prostate androgen-regulated transcript 1 (PART1) has been reported to promote disc degeneration by downregulating the miR-93/MMP2 pathway in NP cells." (PMID 35159202, 2022).
endometriosis (1 paper, 2025). The growth of functional endometrial tissue in anatomic sites outside the uterine body. "A transcriptomic analysis revealed key miRNAs and lnCRNA implicated in endometriosis and RIF, including miR-9, miR-34, and miR-135a/b miR-30d-5p, PART1, MIR17HG, H19, LINC00173, NEAT1, and LINC01960-201." (PMID 39858500, 2025).
head and neck cancer (1 paper, 2024). A primary or metastatic malignant neoplasm affecting the head and neck. "The aim of this study was to determine the role of lncRNA PART1 and downstream FUT6 in tumorigenesis and progression of head and neck cancer (HNC)." (PMID 38807207, 2024).
ischemia (1 paper, 2023). A hypoperfusion of the BLOOD through an organ or tissue caused by a PATHOLOGIC CONSTRICTION or obstruction of its BLOOD VESSELS, or an absence of BLOOD CIRCULATION. "Animal studies on the involvement of PART1 in non-malignant disorders (MPTP: methyl-4-phenyl-1, 2, 3, 6-tetrahydropyridine hydrochloride, I/R: Ischemia-Reperfusion, EF: ejection fraction, FS: fraction shortening, ↑: increase, ↓: decrease)." (PMID 36875771, 2023).
keloid (1 paper, 2022). An irregularly shaped, elevated mark on the skin caused by deposits of excessive amounts of collagen during wound healing. "PPARGC1A, PPARG, PLIN1, LPL, ABHD5, lncRNA PART1, lncRNA ENTPD3-AS1 in trunk keloid and DGAT2 in ear keloid showed decreased trend under paired comparation." (PMID 35677827, 2022).
nasopharyngeal carcinoma (1 paper, 2023). A carcinoma arising from the nasopharyngeal epithelium. "Moreover, lncRNA PART1 has also been reported to be suppressed in nasopharyngeal carcinoma cells." (PMID 37476905, 2023).
Parkinson disease (1 paper, 2023). A progressive degenerative disorder of the central nervous system characterized by loss of dopamine producing neurons in the substantia nigra and the presence of Lewy bodies in the substantia nigra and locus coeruleus. "Two different studies in animal models have shown the importance of PART1 in myocardial ischemia-reperfusion injury and Parkinson’s disease." (PMID 36875771, 2023).
preeclampsia (1 paper, 2022). Preeclampsia is a hypertensive disorder of pregnancy that is characterized by new-onset hypertension with proteinuria presenting after 20 weeks of gestation, and depending on mild or severe forms may initially present with severe headache, visual disturbances, and hyperreflexia. "Six lncRNAs were validated and differentially expressed (p < 0.05) in the preeclampsia and control placentas: UCA1 and HCG4 were found upregulated, and LOC101927355, LINC00551, PART1, and NRAD1 downregulated." (PMID 35740273, 2022). "The qRT-PCR results indicated that LOC101927355, LINC00551, PART1, and NRAD1 were downregulated in the preeclampsia placenta samples (p = 0.009, p = 0.012, p = 0.004, p = 0.001, respectively) compared to the control placentas." (PMID 35740273, 2022). "The present study uncovered the downregulation of LOC101927355, LINC00551, PART1, and NRAD1 and the upregulation of HCG4 in the preeclampsia placentas." (PMID 35740273, 2022).
renal clear cell carcinoma (1 paper, 2022). "At the same time, the lncRNA PART1 is also involved in the progression of renal clear cell carcinoma." (PMID 35223835, 2022).
triple-negative breast carcinoma (1 paper, 2021). An invasive breast carcinoma which is negative for expression of estrogen receptor (ER), progesterone receptor (PR), and human epidermal growth factor receptor 2 (HER2). "Our study suggests that PART1 represents an attractive target for the treatment of triple-negative breast cancers." (PMID 34072264, 2021). "We show that the lncRNA PART1 is enriched in triple-negative breast cancers and cancer stem cell populations." (PMID 34072264, 2021).
tumor (29 papers, 2018 to 2025). "Since dysregulation of PART1 in tumor tissues has been associated with aggressive behavior of cancer cells, PART1 can be regarded as a prognostic factor in different types of cancers." (PMID 36875771, 2023). "Given that basal-like/TNBCs have higher proportions of tumor-initiating CSCs relative to other subtypes, we wondered if PART1 expression is also associated with CSCs." (PMID 34072264, 2021). "Previous studies reported that PART1 was associated with poor prognosis and tumor recurrence in stage I-III non-small cell lung cancer." (PMID 30367091, 2018). "For example, previous studies have shown that PART1 is associated with apoptosis in tumor cells." (PMID 39029955, 2024). "Previous research demonstrated that PART1 was associated with tumor cell apoptosis in cancer." (PMID 33865422, 2021). "In bladder cancer, lncRNA PART1 is a tumour-inhibiting factor that helps to inhibit tumour proliferation and invasion and promote apoptosis." (PMID 38807207, 2024). "Low expression of lncRNA PART1 can significantly promote tumor growth, manifested as an increase in tumor weight and volume." (PMID 38807207, 2024). "PART1, also known as prostate androgen-regulated transcript 1, was identified in exosomes and affected tumor progression via the miR-17-5p/SOCS6 axis and miR-302a-3p/CDC25A axis." (PMID 38279317, 2024). "Different study groups have evaluated functional consequences of PART1 up-regulation or silencing on tumor formation in xenoraft models." (PMID 36875771, 2023). "Similar to in vitro studies, both tumor suppressor role and oncogenic role have been reported for PART1." (PMID 36875771, 2023). "We observed that PART1 significantly expressed higher in tumor group compared to normal group through GSE46602, GSE32571, and GSE62872." (PMID 36144737, 2022). "WGCNA and Kaplan-Meier survival analysis revealed that 5 DELs (MIR4435-2 HG, CASC9, LINC01980, STARD4-AS1 and MIR99AHG) were significantly correlated with OS of HNSCC patients, whereas DEL PART1 was most significantly correlated with the HNSCC tumor." (PMID 34898376, 2021). "Depending on the function and abundance of the mRNAs targeted by the miRNAs, sponging of miRNAs by PART1 can result oncogenic or tumor suppressive effects." (PMID 34072264, 2021). "High PART1 expression was closely correlated with tumor size, T classification, clinical stage, and vascular invasion, and predicted a poor overall survival." (PMID 33865422, 2021). "PART1 is decreased in tumor cells and tissues, which is closely related to poor prognosis of GC patients." (PMID 35155211, 2021). "Mechanistically, PART1 acts as a role of tumor suppressor by interacting with androgen receptor (AR) and stimulating the PLZF gene expression in GC cells." (PMID 35155211, 2021). "By statistical analyses, high PART1 expression was shown to be correlated with tumor size, T classification, clinical stage and vascular invasion (P < 0.05)." (PMID 33865422, 2021). "The ability of lncRNA PART1 to suppress tumours by sponging miR-190a-3p suggested that lncRNA PART1 affects the function of miR-190a-3p by inactivating the AKT pathway." (PMID 34484336, 2021). "Based on its miRNA sponging activity, it is unsurprising that PART1 can have both oncogenic and tumor suppressive effects." (PMID 34072264, 2021). "Most importantly, PART1 showed the strongest correlation with HNSCC tumor across all co-expression modules constructed by WCGNA, suggesting its potential as a diagnostic biomarker to detect preneoplastic HNSCC earlier." (PMID 34898376, 2021). "A recent study revealed that lncRNA PART1 can suppress tumours by regulating miR-190a-3p and subsequently inactivating the AKT pathway." (PMID 34484336, 2021). "To assess the role of PART1 in vivo, we injected HCC1806 scramble control and PART1 knockdown cells into the mammary fat pads of several NOD/SCID mice and found that PART1 knockdown significantly decreased tumor volumes and tumor weights." (PMID 34072264, 2021).
tumor (continued). "Our results indicated that the expression of KLKB1 (P < 0.01), IL13RA2 (P < 0.01), ABCC8 (P < 0.01), and PART1 (P < 0.0001) was consistent with our bioinformatics analysis, which was significantly up-regulated in PanNETs compared with the non-tumor tissues." (PMID 31607839, 2019). "The expression of PART1 was significantly downregulated in the xenograft tumor tissues injected with PART1‐sh (P < .001), while miR‐635 was upregulated." (PMID 31436388, 2019). "The intratumoral injection of lentiviral vector with PART1 knocking down inhibited tumor growth, wherein the tumor volume and weight were dramatically decreased compared to that of scramble (P < .01)." (PMID 31436388, 2019). "To further investigate the clinical application of PART1 in NSCLC, we inoculated A549 cells transfected with PART1‐sh into nude mice and detect the effect of PART1 knocking down on xenograft tumor growth." (PMID 31436388, 2019). "In addition, animal experiments have also shown that low expression of lncRNA PART1 can promote tumor growth." (PMID 38807207, 2024). "Moreover, in order to determine the effects of lncRNA PART1 on tumor cell proliferation, apoptosis and migration, we also conducted validation experiments in another type of HNC cells, namely FaDu cells." (PMID 38807207, 2024). "Moreover, in vivo animal experiments have also proved that downregulation of lncRNA PART1 can promote tumor growth." (PMID 38807207, 2024). "The lncRNA prostate androgen regulates transcript 1 (PART1) is androgenically regulated in human prostate cancer cells and may play a tumour suppressor role in prostate cancer." (PMID 38807207, 2024). "These in vivo experimental results showed that overexpression of FUT6 could block tumor growth, while low expression of lncRNA PART1 could promote tumor growth." (PMID 38807207, 2024). "In vitro experiments to examine expression and function of PART1 in malignancies in which PART1 has been up-regulated (TCLs: tumor cell lines, NCL: normal cell line, ∆: knockdown or deletion, EMT: epithelial-mesenchymal transition, Brdu: Bromodeoxyuridine, DDP: cisplatin, ↑: increase, ↓: decrease)." (PMID 36875771, 2023). "In addition, dysregulation of PART1 has been associated with TNM stage, metastasis, tumor grade and diameter as well as histological type in a variety of cancers." (PMID 36875771, 2023). "Furthermore, we observed that high PART1 expression was correlated with tumor size, T classification, clinical stage, and vascular invasion, and predicted a poor overall survival." (PMID 33865422, 2021). "Ki‐67 protein, cellular marker for cell proliferation, was downregulated in the xenograft tumor tissues injected with PART1‐sh by means of immunohistochemistry, the number of Ki‐67+ cells in the tumor tissues injected with PART1‐sh was also less than that of scramble." (PMID 31436388, 2019). "These suggested that lncRNA PART1 might be a tumor suppressor of OSCC." (PMID 37476905, 2023). "We revealed that expression levels of PART1 and FOXC2 are significantly upregulated and the miR-3529-3p expression level significantly decreases in the serum while high expression level of PART1 is positively associated with tumour size, BCLC stage, and TNM stage." (PMID 34484336, 2021). "We investigated the functional role of lncRNA PART1 in HNC cells by knocking down and overexpressing lncRNA PART1 expression levels in tumor cells." (PMID 38807207, 2024). "Two other studies suggested miR-590-3p played an intermediate tumor suppressor role in the LINC0016/miR-590-3p/ROCK and PART1/miR-590-3p/HMGB2." (PMID 37138218, 2023). "Our bioinformatics data illustrated that lncRNAs PART1, UCA1, DIRC3, HOTAIR, and HOXA11AS have more differential expression in the tumor tissues versus normal counterpart margins." (PMID 35949302, 2022). "Knockdown of PART1 in TNBC cell lines and a patient-derived xenograft decreased cell proliferation, migration, tumor growth, and mammosphere formation potential." (PMID 34072264, 2021).
tumor (continued). "In our ceRNA network, low PART1 expression reduced levels of NR3C2 mediated by mir-301b, and reduced expression of NR3C2 promotes tumor cell proliferation, metastasis and epithelial-to-mesenchymal transition." (PMID 30755833, 2019). "Furthermore, we performed qRT-PCR analysis of tumour tissues and adjacent normal tissues from nineteen HNC patients to determine the expression levels of lncRNA PART1." (PMID 38807207, 2024). "In contrast, PART1 knockdown upregulated PPP2R3A, which is a suspected tumor suppressor." (PMID 34072264, 2021). "The results showed that the expression of KLKB1 (P < 0.01), IL13RA2 (P < 0.01), ABCC8 (P < 0.01), and PART1 (P < 0.0001) was significantly up-regulated, while PCSK2 (P < 0.01) was significantly down-regulated in PanNET tissues compared to the non-tumor tissues." (PMID 31607839, 2019).
cancer (19 papers, 2001 to 2024). A tumor composed of atypical neoplastic, often pleomorphic cells that invade other tissues. "LncRNA PART1 is aberrantly expressed in various human cancers and is associated with abnormal proliferation, migration, invasion, apoptosis and poor prognosis." (PMID 39029955, 2024). "The lncRNA prostate androgen-regulated transcript 1 (PART1) has recently been implicated in the pathogenesis of various cancers." (PMID 39029955, 2024). "Diagnostic value of PART1 has been assessed in few types of cancers, including esophageal and lung cancers revealing promising results." (PMID 36875771, 2023). "The lncRNA prostate androgen-regulated transcript 1 (PART1) was implicated in the process of several cancer pathogeneses." (PMID 34484336, 2021). "Moreover, modulation of expression of PART1 in cancer cell lines or animal models of cancers have been associated with therapeutic benefits." (PMID 36875771, 2023). "Diagnostic role of PART1 has been assessed in some types of cancers." (PMID 36875771, 2023). "PART1 has also been found to be is enriched in triple negative breast cancer cells and in Aldefluorhigh cancer stem cells." (PMID 36875771, 2023). "Functional studies in a variety of cancer-derived cell lines have assessed the consequences of up-regulation or silencing of PART1." (PMID 36875771, 2023). "Since abnormal expression of PART1 has been reported in a variety of cancers, it is possible that expression levels of PART1 can differentiate cancerous tissues from normal counterparts with appropriate diagnostic power." (PMID 36875771, 2023). "The Cancer Cell Line Encyclopedia (CCLE) reports the remarkable co-expression relationships between PART1 and the surface marker-coding genes of NK cells." (PMID 36304284, 2022). "The roles of PART1 in the progression of several human cancers have been well documented in the previous investigations." (PMID 33865422, 2021). "Only some lncRNAs, including MAGI2-AS3, PART1, LINC00675, and LINC00473 were reported to be linked with cancer growth." (PMID 34335862, 2021). "Consistent with the oncogenic effects of PART1 in the TNBC cells, PART1 knockdown downregulated MYO5A, ZHX2 and BICC1, which have all been implicated in cancer progression." (PMID 34072264, 2021). "It would be of interest to perform similar genome-wide analyses on the effects of PART1 in other cancers and tissues to determine if the effects are generally true of PART1, or if they are specific to TNBC." (PMID 34072264, 2021). "Genomic analyses on PART1 in other cancers will likely reveal similar effects; however, the miRNAs and mRNAs that are regulated by PART1 will differ and depend upon the cellular context." (PMID 34072264, 2021). "Long non-coding RNA (lncRNA) prostate androgen-regulated transcript 1 (PART1) was previously shown to exert an oncogenic role in several human cancers." (PMID 33865422, 2021). "Moreover, dysregulation of PART1 expression is regarded as a prognostic factor in a variety of cancers." (PMID 36875771, 2023). "Value of PART1 in cancer diagnosis (ANTs: adjacent normal tissues)." (PMID 36875771, 2023). "In addition to known effects on miR-190-3p, we report novel PART1-mediated regulation of miR-937-5p, miR-22-5p, and miR-30b-3p in TNBC; all of which have been implicated in cancer progression in prior studies." (PMID 34072264, 2021). "PART1 also played a vital role in the occurrence and development of other cancers." (PMID 34178478, 2021). "Therefore, the influence of lncRNA PART1 on the proliferation, apoptosis and migration of cancer cells may occur through regulation of the translation and transcription of FUT6." (PMID 38807207, 2024). "Together, our analyses uniformly suggest that PART1 exerts pro-survival/oncogenic effects in the cancer cells, including within CSC populations, likely due to increased PART1 expression within these populations." (PMID 34072264, 2021). "LncRNA PART1 and FUT6 play critical roles in tumorigenesis and cancer progression." (PMID 38807207, 2024).
cancer (continued). "Our studies showed that lncRNA PART1 was underexpressed in patients with HNC and that its low expression could promote cancer cell migration and proliferation and inhibit cancer cell apoptosis." (PMID 38807207, 2024). "Aside from PART1, no function has yet been ascribed to these genes, however PART1 has been extensively researched with regards to cancer development and progression." (PMID 37752916, 2023). "Taken together, PART1 participates in the pathogenesis of cancer and a variety of non-cancerous conditions including neurodegenerative disorders." (PMID 36875771, 2023). "The current review provides a concise but comprehensive summary of the role of PART1 in different cancers and non-malignant disorders." (PMID 36875771, 2023). "However, another study in this type of cancer has revealed up-regulation of PART1 in the sera samples of gefitinib non-responders versus responders." (PMID 36875771, 2023). "Orilnc1, KIMAT1, SLCO4A1-AS1, LINC01420, KRAS1P, YWHAE, PART1, MALAT1, PCAT-1, lncRNA-NUTF2P3-001 and TP53TG1 are long non-coding RNAs (lncRNAs) whose interactions with KRAS have been verified in the context of cancer." (PMID 35139853, 2022). "We further studied the expression of PART-1 in 27 paired (from the same patient) cancerous and non-cancerous prostatic tissues, with qualitative and quantitative RT-PCR (LightCycler®technology), in order to examine whether PART-1 is overexpressed or underexpressed in cancer." (PMID 11487271, 2001).
PART1 also shares sentences with these, for which no sentence is quoted: glioblastoma (4 papers); fibroids (2); cervical cancer (1); colon cancer (1); degenerative disease (1); head and neck squamous cell carcinoma (1); laryngeal carcinoma (1); Obesity (1); squamous cell lung carcinoma (1).